MEN1 (menin 1)
Diseases named in the same sentence as MEN1 in open-access papers (continued):
Sharing a sentence is not in itself a finding about the gene and the disease.
tuberous sclerosis (16 papers, 2020 to 2025). Hereditary disease characterized by seizures, intellectual disability, developmental delay, and skin and ocular lesions. "In MEN1, the most frequent location is facial, mainly the upper lip, in contrast with tuberous sclerosis, where this location is spared." (PMID 36428828, 2022). "Apart from MEN1, multiple facial angiofibromas can be found in Birt-Hogg-Dubé syndrome and tuberous sclerosis as well." (PMID 36428828, 2022). "Finally, using the validated model, they explored the efficacy of and resistance to mTORC1 inhibition, with results suggesting that patients with MEN1 loss are more likely to benefit (experience control to a quiescent phenotype) compared to patients with tuberous sclerosis (TSC) or DAXX loss." (PMID 39949335, 2025). "Additionally, 4 paediatric patients aged 11–14 years had CD associated with a family history of genetically-confirmed MEN1 (n = 2), clinical features of MEN1 (n = 1) or a TSC2 mutation-positive tuberous sclerosis (n = 1)." (PMID 33515368, 2021). "We set up a model able to represent frequently reported PanNETs drivers in patient cohorts, such as Menin-1 (MEN1), Death domain associated protein (DAXX), Tuberous Sclerosis (TSC), as well as wild-type tumors." (PMID 37270586, 2023). "In contrast with angiofibromas in MEN1, the angiofibroma of a patient with tuberous sclerosis did not exhibit allelic deletion." (PMID 36428828, 2022). "Roughly 10% of cases are related to familial endocrine tumor syndromes and include multiple endocrine neoplasia type 1 (MEN1), von-Hippel Lindau disease (VHL), neurofibromatosis type 1 (NF-1), and tuberous sclerosis (TSC)." (PMID 37568572, 2023).
pancreatic cancer (15 papers, 2018 to 2025). "In twenty index cases undergoing mutational analysis in this study, none of the ten patients presenting with tumors of parathyroids and pituitary glands tested positive for MEN1 mutation, vs. 60% of patients in whom phenotype included a pancreatic tumor." (PMID 30254610, 2018). "However, in some cases, MEN1-associate pancreatic tumors exhibit a more aggressive behavior than the sporadic forms, with metastasis described in about 23–33% of cases." (PMID 33919851, 2021). "Compared with sporadic PanNET, pancreatic tumors arising in MEN1 patients are characterized by early-onset and multiple pancreatic microadenomas, which can ultimately progress to larger tumors and are often the first neoplastic cause for MEN1 patients' mortality." (PMID 32850899, 2020). "The father of the present patient had died for pancreatic cancer before the index patient was confirmed as an MEN1 patient." (PMID 34160414, 2021). "Our interest was to introduce a PET tracer for the detection of early pancreatic neoplasms in MEN1 patients." (PMID 29335487, 2018). "Children with MEN1 had significantly higher number of pancreatic tumors compared to sporadic cases." (PMID 37152923, 2023). "Notably, epigenetic modifiers frequently showed more mutations in AYAs, including H3F3A, KDM5A and IDH1/2 in glioma, EP300 in liver cancer, SMARCA4 in ovarian cancer, and MEN1 in pancreatic cancer." (PMID 36433963, 2022). "Similarly, the high rate of pancreatic cancer may reflect misclassification, where aggressive DPNENs characteristic of MEN1 are potentially miscoded as pancreatic adenocarcinomas." (PMID 40607214, 2025).
Angiofibroma (14 papers, 2015 to 2025). A benign neoplasm of fibrous tissue in which there are numerous small and large, frequently dilated, vascular channels. "The E359K mutation was found in an angiofibroma, a skin tumor type known to be affected by MEN1 gene mutations." (PMID 35941657, 2022). "Similar to MEN1-associated angiofibromas, collagenomas are usually multiple with 83% of MEN1 patients diagnosed with a collagenoma having at least three or four lesions." (PMID 36325452, 2022). "To our surprise, we noted a decreased frequency of angiofibromas and collagenomas in patients with variants affecting central cavity of the menin structure, which could suggest an alternative pathomechanism for MEN1-related skin manifestations." (PMID 39946193, 2025). "Previous reports from our center, which included comprehensive dermatologic evaluation of patients with MEN1, had revealed a prevalence of 64%–88% for angiofibromas and 62%–72% for collagenomas." (PMID 39946193, 2025). "The penetrance of these lesions increases with age in MEN1 (85% for angiofibromas and 70% for collagenomas by age 40)." (PMID 39946193, 2025). "Angiofibromas/collagenomas can rarely be an initial manifestation of MEN1 and identifying these lesions in a patient presenting with another MEN1-defining tumor or having a strong family history of MEN1 can help to secure the clinical diagnosis." (PMID 36325452, 2022). "Angiofibromas in MEN1 patients are reported with a frequency between 11% and 88% on studies of different sample size (varying from 145 to 5 patients)." (PMID 36428828, 2022). "Angiofibromas were present in 64% of the MEN1 patients and only 8% of the individuals with sporadic ZES." (PMID 36428828, 2022). "Long recognized but often unappreciated as a component of the clinical phenotype, the skin manifestations of MEN1 include angiofibromas and collagenomas." (PMID 36325452, 2022). "The prevalence of angiofibromas in comprehensively screened MEN1 patients ranges from 22-88% depending on the population." (PMID 36325452, 2022). "Even though angiofibromas are the most frequent cutaneous tumors in MEN1, differential diagnosis with other cutaneous tumors should be taken into account." (PMID 36428828, 2022). "MEN1-related angiofibromas are true neoplasms that arise from cells with a mesenchymal immunophenotype that are concentrated in a perivascular location." (PMID 36325452, 2022). "In MEN1 patients with any angiofibroma, multiple lesions are identified in most patients: 33% have ≥ three, 77% have > three, and 57% have > four angiofibromas." (PMID 36325452, 2022). "By age 40, the penetrance of angiofibromas and collagenomas in MEN1 patients has previously been estimated to be 85% and 70%, respectively." (PMID 36325452, 2022). "Characteristic MEN1-related skin lesions (angiofibromas, collagenomas, hyperpigmentation) were present in all of the screened family members." (PMID 33807230, 2021). "Angiofibromas and collagenomas tend to be multiple and are more common in patients with MEN1 than in the general population (64% vs. 8% and 62% vs. 5%, respectively)." (PMID 31263451, 2019). "The prevalence of angiofibromas in our MEN1 mutation-positive patients was significantly higher compared to that of MEN1 mutation-negative." (PMID 37484956, 2023). "In the whole cohort of familial cases, we observed a higher prevalence of angiofibromas in MEN1 mutation-positive compared to MEN1 mutation-negative (OR = 4.5, p = 0.003), also after adjustment for age." (PMID 37484956, 2023). "The mutation resulting in menin E359K was found in a sporadic angiofibroma, a skin tumor type known to be associated with MEN1, without LOH at the WT locus." (PMID 35941657, 2022). "There are high quality data to support that angiofibromas and collagenomas are causally related to alterations affecting the MEN1 gene, but cutaneous melanoma should not be considered part of the MEN1 clinical spectrum." (PMID 36325452, 2022).
Angiofibroma (continued). "the model identified the relation between the phenotype “angiofibromas” and the gene “MEN1”." (PMID 30616557, 2019). "The presence of angiofibromas and/or collagenomas may be a strong indicator of the diagnosis of MEN1." (PMID 31263451, 2019). "None of the 19 angiofibromas had loss of heterozygosity of the MEN1 gene." (PMID 36428828, 2022). "Angiofibromas were seen in 55/162 (34%) patients in genotype-positive disease and 1/47 (2%) with genotype-negative MEN1 (P < 0.0001)." (PMID 39946193, 2025). "An angiofibroma diagnosis is usually made clinically in a patient with known MEN1 but a biopsy can facilitate the diagnosis in someone not known to be affected." (PMID 36325452, 2022). "Despite not being incidental, angiofibromas in MEN1 are still incompletely described in terms of correlations with clinical endocrine phenotype and genetic background." (PMID 36428828, 2022). "More than three angiofibromas were found in 50% of the MEN1 patients, while none of the patients with sporadic ZES met this criterion." (PMID 36428828, 2022). "Most likely to be multiple in MEN1 patients and with no clear genotype-phenotype correlations, angiofibromas and collagenomas are primarily identified in adults." (PMID 36325452, 2022). "Angiofibromas are also not pathognomonic for MEN1 or TSC and can occur sporadically." (PMID 36325452, 2022). "However, like angiofibromas and collagenomas, the exact prevalence is difficult to ascertain due to the lack of large studies of MEN1 patients undergoing a comprehensive evaluation." (PMID 36325452, 2022). "MEN1-related angiofibromas differ from those seen in TSC, in which the lesions are larger, more numerous, and earlier in onset; in TSC, the angiofibromas are also predominantly in a malar distribution and do not appear on the upper lip and its vermilion border as can be seen in MEN1 patients." (PMID 36325452, 2022).
Carney complex (14 papers, 2011 to 2025). Carney complex (CNC) is characterized by spotty skin pigmentation, endocrine overactivity and myxomas. "A somewhat surprising finding was that the protein PRKAR1A, known to be mutated and inactivated in patients with the inherited disease Carney Complex, was increased two-fold in MEN1-KO-BON1 cells relative to BON1 cells." (PMID 32884006, 2020). "A genetic defect is evident in some cases; known genetic changes include: multiple endocrine neoplasia type 1 (MEN1); Carney complex; McCune-Albright syndrome; and, more recently identified, aryl hydrocarbon receptor-interacting protein (AIP)." (PMID 22024364, 2011).
neurofibromatosis type 1 (14 papers, 2014 to 2025). A clinically heterogeneous, neurocutaneous genetic disorder characterized by cafe-au-lait spots, iris Lisch nodules, axillary and inguinal freckling, and multiple neurofibromas. "Pancreatic NENs may be sporadic or arise in the context of an inherited syndrome such as multiple endocrine neoplasia type 1 (MEN1) or type 4 (MEN4), von Hippel‒Lindau (VHL) disease, neurofibromatosis type I (NF1), and tuberous sclerosis." (PMID 37103745, 2023). "However, 10% of PanNETs may occur in hereditary syndromes, such as multiple endocrine neoplasia type 1 (MEN1), Von Hippel—Lindau disease (VHL), type 1 neurofibromatosis (NF1), and tuberous sclerosis complex (TSC)." (PMID 35163032, 2022).
Hypoglycemia (13 papers, 2014 to 2026). A decreased concentration of glucose in the blood. "The conditional knockout of β-catenin in Men1-deficient PNETs suppresses tumorigenesis and significantly improves hypoglycemia and the survival rate in mice." (PMID 25517963, 2014). "The blockade of β-catenin markedly improved the hypoglycemia in the Men1-deficient mice." (PMID 25517963, 2014). "Taken together, these findings indicate that the suppression of β-catenin signalling by a small molecule antagonist could effectively inhibit the Men1-deficient tumour proliferation and prevent hypoglycemia in vitro and in vivo." (PMID 25517963, 2014). "A 30-year-old man with MEN1, who was also diagnosed with nesidioblastosis and hypoglycemia, had an additional growth hormone-releasing hormone (GHRH) producing tumor, hyperparathyroidism, hyperprolactinemia, and multiple endocrine pancreatic tumors." (PMID 37371827, 2023). "A 28-year-old woman with known MEN1 presented with postprandial hypoglycemia in the second trimester of pregnancy." (PMID 37908256, 2022). "In our cohort, children did not present with any specific clinical features but hypoglycemia and, therefore, were tested for the MEN1 mutations only." (PMID 37152923, 2023). "The hypoglycemia and mortality in Men1 knockout mice with PNETs could be markedly ameliorated by the blockade of β-catenin signalling." (PMID 25517963, 2014). "However, not all patients with MEN1 and islet cell changes exhibited clinical symptoms of hypoglycemia." (PMID 37371827, 2023). "Patients with MEN1 often present with multiple pNETs, which may exhibit multihormonal secretion and frequently cosecrete GHRH and insulin in MEN1, while hypoglycemia may not be manifested possibly due to GH and insulin's counteractive effects on glucose metabolism." (PMID 42007244, 2026).
metastatic disease (13 papers, 2017 to 2025). "Multiplex immunohistochemistry (mIHC) analysis showed a more prominent immunosuppressive environment in metastatic tumors, especially in patients with MEN1/DAXX mutations." (PMID 38448900, 2024). "Although our patient had no radiographic evidence of additional intra-pancreatic or distant metastatic disease, he remains at significant risk for additional or recurrent disease due to his known multifocal disease and MEN1 mutation and will require close follow-up." (PMID 34118524, 2021). "The pancreatic and thyme NETs are the deadliest of the MEN1 lesions and they often develop into metastatic disease." (PMID 31527438, 2019). "Alterations in MEN1 (NGS) were less associated with having high-grade PanNETs and metastatic disease at diagnosis." (PMID 31692857, 2019). "MEN1 alterations by next-generation sequencing (NGS) were less associated with having high-grade PanNETs and metastatic disease at diagnosis (p ≤ 0.05)." (PMID 31692857, 2019). "One was a cohort of 105 patients with MEN1 from the US, which observed that 94% [16/17] of patients with metastatic tumors had type O blood compared to 74% [32/43] of patients with a benign tumor who had non-O blood type." (PMID 28903383, 2017). "As some studies on sporadic panNETs have demonstrated that CgA and PP can predict metastatic disease, it is possible that repeat biomarker measurement could be useful for the early detection of metastatic disease in MEN1 as well." (PMID 40455177, 2025). "Alterations in MEN1 (NGS) and age >54 were less associated with metastatic disease at diagnosis." (PMID 31692857, 2019). "Our data suggest that MEN1 alterations are an early event in tumorigenesis and that ATRX/DAXX variants may be later events in disease progression or occur more frequently in patients presenting with metastatic disease." (PMID 29212165, 2017). "One possible reason for better survival rates after surgery is that an early operation for MEN1-ZES, independent from the type of duodenopancreatic procedure, prevents the development of distant metastatic disease, which is the most life-threatening factor." (PMID 35454834, 2022). "In our study, we integrate large publicly available datasets of PANETs to show a remarkably conserved MEN1- and DAXX/ATRX-driven metastatic disease progression." (PMID 32345369, 2020).
Zollinger-Ellison syndrome (12 papers, 2014 to 2026). Zollinger-Ellison syndrome (ZES) is characterized by severe peptic disease (ulcers/esophageal disease) caused by hypergastrinemia secondary to a gastrinoma resulting in increased gastric acid secretion. "Pancreatic gastrinomas are usually single large sporadic tumours; and while they may occur in patients with MEN1 they are seldom the cause of symptomatic Zollinger-Ellison syndrome in this cohort." (PMID 28965289, 2017). "Approximately 1/3 of patients with Zollinger-Ellison syndrome will carry a MEN-1 mutation." (PMID 26542689, 2015). "Another study from the NIH in 2004 described the characteristics of 107 MEN1 patients with Zollinger-Ellison syndrome." (PMID 36325452, 2022). "In Pan-NETs, both functioning and non-functioning tumors showed serum CgA levels at 60 ~ 80 times the normal upper levels, particularly in Zollinger-Ellison syndrome in MEN1 cases with serum CgA levels being 80 ~ 100 times higher than the normal upper levels." (PMID 33485291, 2021). "MEN-1 is known to occur in conjunction with Zollinger-Ellison Syndrome (ZES) in both sporadic and heritable forms, with an estimated 50% penetration among blood relatives." (PMID 24910640, 2014). "Melanoma was found in three patients (3%), but in a concomitant literature review of 1009 cases of MEN1 and Zollinger-Ellison syndrome, there were no melanomas found." (PMID 36325452, 2022).
familial hypocalciuric hypercalcemia (11 papers, 2009 to 2025). Familial hypocalciuric hypercalcemia (FHH) is a generally asymptomatic genetic disorder of phosphocalcic metabolism characterized by lifelong moderate hypercalcemia along with normo- or hypocalciuria and elevated plasma parathyroid hormone (PTH) concentration. "Other less common causes of PHPT include parathyroid hyperplasia, often observed in multiple endocrine neoplasias types 1 and 2a (MEN1, MEN2A), and inactivating heterozygous mutations of the CaSR gene, associated with most cases of familial hypocalciuric hypercalcemia (FHH)." (PMID 39519190, 2024). "Familiar forms of PHPT (FPHPT) represent less than 5% of the total PHPT cases and include, among others, familial hypocalciuric hypercalcemia (FHH) and multiple endocrine neoplasia types 1 and 2A (MEN1 and MEN2A)." (PMID 34556169, 2021). "Therefore she was referred to our hospital, where she was screened for MEN1, MEN2A and familial benign hypocalciuric hypercalcemia (FHH) because of the youth at diagnosis of osteoporosis." (PMID 36998475, 2023). "Hereditary forms of PHPT account for approximately 10-15% of all cases and encompass syndromes such as MEN1, MEN2A, MEN4, MEN5, HPT-JT, familial hypocalciuric hypercalcemia (FHH), and familial isolated hyperparathyroidism (FIHP)." (PMID 41210508, 2025).
familial isolated hyperparathyroidism (11 papers, 2000 to 2025). A rare, autosomal dominant hereditary syndrome characterized by hypercalcemia, abnormally high levels of parathyroid hormone, and isolated hyperfunctioning parathyroid tumors. "Non-syndromic hereditary hyperparathyroidism, called familial isolated hyperparathyroidism (FIHP), can be caused by the incomplete manifestation of mutations of syndrome-related genes such as MEN-1, CDC73, GCM2, CDKN1A, CDKN1B, or CDKN2C." (PMID 36900197, 2023). "Familial isolated hyperparathyroidism (FIHP) may be due to incomplete penetrance of mutations causing syndromic PHPTs, as the genes found in FIHP overlap, for example, MEN1, CDC73, or CASR." (PMID 38038882, 2024). "However, there is also increasing evidence that familial or de novo germline mutations cause PHPT as either part of a multiple tumor syndrome, e.g., MEN1, or isolated PHPT, e.g., familial isolated hyperparathyroidism (FIHP)." (PMID 38038882, 2024).
familial isolated pituitary adenoma (11 papers, 2019 to 2025). "In some instances, CD is a manifestation of genetic mutation syndromes that include multiple endocrine neoplasia type 1 (MEN1), familial isolated pituitary adenoma (FIPA), and Carney complex." (PMID 36359740, 2022). "Less than 5% of the cases are related to a hereditary syndrome, such as Multiple Endocrine Neoplasia 1 and 4 (MEN1 and MEN4, respectively), familial isolated pituitary adenoma (FIPA) or Carney complex." (PMID 31522358, 2020). "Prolactin secreting adenomas can be part of genetic syndromes, such as multiple endocrine neoplasia type 1 (MEN1) or type 4 (MEN4), familial isolated pituitary adenoma (FIPA) or Carney complex." (PMID 31847209, 2019). "The first category of tumors with recurrent genetic mutations are those that arise due to familial syndromes which include McCune-Albright syndrome, multiple endocrine neoplasia types 1 and 4 (MEN1 and MEN4), familial isolated pituitary adenomas (FIPA), and Carney complex." (PMID 31139150, 2019).